GATA3 (GATA binding protein 3)
Diseases named in the same sentence as GATA3 in open-access papers (continued):
Sharing a sentence is not in itself a finding about the gene and the disease.
breast carcinoma (continued). "Together, the present study suggested that lncRNA LOC645166 mediated adriamycin chemoresistance in breast cancer by regulating GATA3 via NF-κB." (PMID 32461377, 2020). "Knockdown of FOXP1 decreased gene expression of Gata3 and Esr1, along with diminishing ERα protein expression in WT mouse mammary epithelial cells as well as in human breast cancer cells, MCF7." (PMID 32934200, 2020). "In breast cancer, suppression of ELK3 in MDA-MB-231 cells resulted in the loss of metastatic characteristics, mainly by activating GATA binding protein 3 (GATA3) to regulate the expression of cell-cell adhesion factors and tight junctional proteins." (PMID 32104682, 2020). "GATA3 has been reported as a sensitive and specific marker for urothelial and breast carcinomas in tissue sections." (PMID 31636361, 2020). "Rescue assays were carried out to demonstrate the role of lncRNA LOC645166/NF-κB/GATA3 axis in regulating the adriamycin tolerance in breast cancer cells." (PMID 32461377, 2020). "Mechanistically, lncRNA LOC645166 recruits NF-κB to the promoter region of GATA3 and promotes its transcription, eliciting adriamycin resistance in breast cancer cells." (PMID 32461377, 2020). "Noteworthy was that a handful of genes from this network had been annotated as TSGs either specifically in relation to breast cancer (GATA3, RERG, and SIAH2) or in other types of cancer (DOC2A and RGS22)." (PMID 32605588, 2020). "In conclusion, we have shown that lncRNA LOC645166 and GATA3 are up-regulated in adriamycin-resistant breast cancer cell lines and tissues." (PMID 32461377, 2020). "The high expression of GATA3, in turn, was correlated with the level of estrogen receptor-α (ER), which is a highly significant marker of sensitivity to hormonal therapy in breast cancer patients." (PMID 32225066, 2020). "Increased GATA3 turnover mediated by increased proteasomal degradation has previously been reported in breast cancer cells and T cells." (PMID 33298139, 2020). "The interaction between GATA3 and miR-29b had been previously reported in breast cancer cells, endothelial cells." (PMID 32760217, 2020). "Consistently, GATA3 expression was higher in xenografts derived from breast cancer cells with shRNA NC compared with that in lncRNA LOC645166 - silencing group following treatment with adriamycin." (PMID 32461377, 2020). "Currently, the role of GATA3 in tumors is focused on malignant tumors of epithelial origin, such as breast cancer, urothelial cancer, prostate cancer, and paraganglioma." (PMID 32760217, 2020).
breast carcinoma (continued). "On January 27th, 2017 a second extraction of CSF is performed and this time cytology confirmed infiltration by breast carcinoma (panCK+, GATA3+)." (PMID 31895768, 2020). "GATA‐3 labeling has been demonstrated to be highly specific for identifying the metastasis of TNBC breast carcinomas in distant sites (e.g., lung and brain) (Sangoi, Shrestha, Yang, Mego, & Beck, 2016)." (PMID 33133558, 2020). "In conclusion, male breast cancers constitute a heterogeneous disease, with a limited number of recurrently mutated genes (PIK3CA, GATA3, and MAP3K1) and numerous genes with pathogenic mutations at lower frequencies." (PMID 32210163, 2020). "Chou demonstrated that GATA3 promotes cell differentiation by inducing miR-29b expression, inhibits cancer cell metastasis and changes the tumor microenvironment of breast cancer, which is consistent with our findings." (PMID 32760217, 2020). "The relationship between GATA3, T-bet, and ER expression in mammary tumors in dogs remains to be defined." (PMID 32225066, 2020). "We found increased levels of GATA3 in benign canine mammary tumors compared to healthy tissue as well as malignant and metastatic tumors." (PMID 32225066, 2020). "Therefore, CCND1 is highly likely to be the gene that mediates rs614367 breast cancer susceptibility: variants in the enhancer region (either rs614367 or other functional variants) may be hypothesized to drive risk by disrupting E2F1/GATA3/MYC/TCF7L2/ZNF217 binding and affecting CCND1 expression." (PMID 30247654, 2019). "GATA3 restoration in breast cancer cell-lines induces miR-29b expression, leading to repressed metastasis and reduced tumor outgrowth." (PMID 31614829, 2019). "GATA3 acts as a pleiotropic modulator of the molecules that are indirect or are immediate effectors of various cellular processes that repress breast cancer metastasis." (PMID 31754326, 2019). "In the present study, we demonstrated that ENTPD3 is a novel downstream effector of GATA3 and acts as a tumor suppressor in human breast cancer by hydrolyzing eATP." (PMID 31754326, 2019). "Specifically, GATA3 accelerated the hydrolysis of eATP and suppressed breast cancer cell metastasis by up-regulating ENTPD3." (PMID 31754326, 2019). "GATA3 decreased only in apocrine, large cell neuroendocrine, metaplastic and pleomorphic breast cancer subtypes." (PMID 30872657, 2019). "By contrast, in breast cancer cells, GATA3, G9A, and NuRD (MTA3) act in a coordinated manner to form a transcription-repression complex that regulates mammary epithelial plasticity by controlling EMT-related gene expression." (PMID 31685800, 2019). "Through this study, we identified possible GATA3-correlated genes and core pathways that play an important role, which requires further investigation in breast cancer." (PMID 30872657, 2019). "Our study implicates the GATA3-UTX-Dicer axis in breast cancer metastasis and provides new mechanistic insights into the pathophysiological function of GATA3." (PMID 31685800, 2019). "In a mouse model of PyMT-induced breast cancer, overexpression of Gata3 in late-stage tumors induces tumor differentiation and suppresses tumor dissemination." (PMID 31013830, 2019). "In detail, the GATA3 mRNA expression level increased in 13 cases compared with one decrease in breast cancer." (PMID 30872657, 2019). "While FOXA1 and GATA3 are significant predictors of favorable outcome in breast carcinoma (longer disease-free interval and overall survival), Nestin expression is associated with a more unfavorable prognosis." (PMID 30819139, 2019). "Our study has identified a novel effector of GATA3, ENTPD3, and provides a distinct perspective on the mechanism involved the GATA3 suppression of breast cancer progression and metastases." (PMID 31754326, 2019).
breast carcinoma (continued). "It has been shown that an FOXN3–NEAT1–SIN3A complex promotes the invasion of breast cancer cells and EMT in vitro and the proliferation and metastasis of breast cancer in vivo by inhibiting the transcription of downstream target genes GATA3 and TJP1." (PMID 31214490, 2019). "GATA3 and FOXA1 are mutated in a mutually exclusive manner, which suggests that a mutation in FOXA1 would also mark a breast cancer that is endocrine therapy sensitive." (PMID 31281796, 2019). "In the cases of mammary and breast cancer cells, overexpression of GATA3 or NOTCH1 in mammary basal cells (BCs) can convert BCs to luminal cells (LCs)." (PMID 31013830, 2019). "To date, little is known about the GATA family expression levels or their possible prognostic value, except for GATA3, in breast cancer." (PMID 30872657, 2019). "We next investigated the roles of GATA3 and UTX in the migration of breast cancer cells in vitro by using the wound-healing assay; overexpression of GATA3 or UTX resulted in a notable delay in wound closure as compared with the control." (PMID 31685800, 2019). "This included 7 breast cancer-related genes: caspase 8 (CASP8), cadherin 1 type 1 (CDH1), estrogen receptor 1 (ESR1), ETS variant 6 (ETV6), forkhead box A1 (FOXA1), GATA-binding protein 3 (GATA3) and neurotrophic tyrosine kinase receptor type 3 (NTRK3)." (PMID 31182966, 2019). "There are no systematic clinicopathological studies of CK7 and GATA3 negative tumors while limited studies are available characterizing the prognostic utility of GATA3 expression in breast cancer." (PMID 31718619, 2019). "The present study showed that GATA3 blocked breast cancer cell motility by up-regulating ENTPD3 expression, which in turn hydrolyzed eATP in the tumor microenvironment." (PMID 31754326, 2019). "This provides additional evidence supporting the viewpoint that GATA3 restrains breast cancer metastasis by altering the tumor microenvironment." (PMID 31754326, 2019). "Given that GATA3 is frequently altered in Luminal A breast cancers, our findings provide an additional molecular layer to the worse prognosis showed by ER+/PR− breast cancers." (PMID 30691046, 2019). "The RNA-Seq expression heatmap showed that GATA3 was significantly increased in breast cancer tissues compared with normal tissues." (PMID 30872657, 2019). "Based on analyses performed through cBioPortal on the largest publicly available breast cancer dataset, Molecular Taxonomy of Breast Cancer International Consortium (METABRIC), 11.5% (250/2173) of breast tumors harbored somatic mutations of GATA3." (PMID 31718619, 2019). "The boxplot of the RNA-Seq expression in 1085 breast cancer tissues vs 291 normal breast tissues demonstrated that GATA3 was significantly increased." (PMID 30872657, 2019). "Another breast cancer driver, GATA3, shifts gene expression towards the face defined by the lipogenic, HER2 and invasion and tissue remodeling tasks and away from the cell division archetype (p = 0.003, hypergeometric test)." (PMID 31780652, 2019). "Here, we demonstrate that GATA3 reduces the ATP level in the breast cancer microenvironment and inhibits breast cancer metastasis by up-regulating ectonucleoside triphosphate diphosphohydrolase 3 (ENTPD3)." (PMID 31754326, 2019). "In conclusion, these experiments indicate that GATA3 recruits UTX to suppress breast cancer metastasis, supporting a role for the GATA3/UTX complex in controlling the metastasis of breast cancer in vivo." (PMID 31685800, 2019). "R software with the limma package was applied to screen DEGs from the gene expression dataset GSE24249 between control vectors and overexpressed GATA3 genes in MDA-MB231 breast cancer cells." (PMID 30872657, 2019).
breast carcinoma (continued). "GATA3 was found to be upregulated and exhibited a favorable value in the diagnosis and prognosis of breast cancer." (PMID 30872657, 2019). "Breast cancer patients with tumors expressing FOXA1 may have a better clinical outcome because FOXA1 and GATA3 are expressed in close association with ERα (Estrogen receptor α), by encoding for transcription factors and have a potential involvement in ERα-mediated breast cancer development." (PMID 30819139, 2019). "Immunoblotting of the primary culture lysates of mammary tumors from Tg-Neu mouse showed high expression of GATA3 (lane 1)." (PMID 31704972, 2019). "Forced expression of GATA3 in mouse mammary cancer model showed a protective effect with improved prognosis." (PMID 31718619, 2019). "To explore the possible roles for Notch3 and GATA-3 in breast cancer, we detected their expression levels in a series of breast cancer cell lines." (PMID 30100605, 2018). "Compared with middle‐aged patients of breast cancer, poorer prognosis of elderly patients may be caused by aging, while poorer prognosis of young patients was probably mediated through intrinsic characteristics, such as basal‐like subtype, GATA3 mutations, and DNAm age of the cancerous tissues." (PMID 29761914, 2018). "Collectively, our results suggest that GATA-3 expression is positively regulated by Notch3 in breast cancer cells." (PMID 30100605, 2018). "Inactivating mutations of BRCA1 and BRCA2 frequently occur in breast cancer as well, while unique mutations in GATA3, PIK3CA, and MAP3K1 are enriched in the luminal A subtype of breast cancer." (PMID 29753129, 2018). "In breast cancer, GATA3 expression is a prominent marker of luminal breast tumors, and loss of GATA3 expression is associated with aggressive tumor phenotypes." (PMID 29535312, 2018). "Herein, we demonstrate a novel mechanism whereby Notch3 inhibit EMT by transcriptionally upregulating GATA-3 expression, at least in part, leading to the suppression of cancer metastasis in breast cancers." (PMID 30100605, 2018). "GATA3 and TBX3 encode transcription factors that are frequently mutated and highly expressed in breast cancer, respectively." (PMID 30323337, 2018). "As already demonstrated in females, both NY-BR-1 and GATA-3 expression in male breast cancer outperforms the use of mammaglobin and BRST-2 alone." (PMID 29116378, 2018). "Our results provide novel insights into the complex regulation of EMT and provide a basis for further delineation of the Notch3/GATA-3 pathway as a promising candidate of prognostic indicator and/or therapeutic avenue for breast cancers." (PMID 30100605, 2018).
breast carcinoma (continued). "As expected for transcription factors, clear nuclear signal intensity was observed for ERα, FOXA1, and GATA3 in the primary breast cancers as well as the metastatic samples." (PMID 29972720, 2018). "Together, these findings suggest a functional and positive correlation between Notch3 and GATA-3 during EMT in breast cancer." (PMID 30100605, 2018). "Although GATA3 levels remained unaltered between primary breast cancer and pleural metastases, FOXA1 levels were reduced exclusively in metastases of patients who received endocrine therapies in the adjuvant setting, even though ERα was still expressed." (PMID 29972720, 2018). "GATA-3 is essential for the development of human mammary gland and the differentiation breast cancer cell." (PMID 30100605, 2018). "FOXA1 and GATA3, both well recognized as luminal breast cancer‐defining genes, play crucial roles in genomic functions of ERα." (PMID 29972720, 2018). "Of all the GATA family factors, GATA-3 is considered an emerging and specific biomarker of breast cancer that shows less invasive, has fewer metastases, and therefore associates with a better prognosis." (PMID 30100605, 2018). "In the present study, we present solid evidence demonstrating that activated Notch3 maintains the epithelial phenotype and suppresses metastasis through the transcriptional regulation of GATA-3 in breast cancer." (PMID 30100605, 2018). "The sensitivity of mammaglobin vs GATA-3 in labelling male breast cancer was 73.3 vs 100%, and BRST-2 vs GATA-3 was 60 vs 100%, respectively." (PMID 29116378, 2018). "We demonstrate in vitro and in vivo that Notch3 suppressed EMT and breast cancer metastasis by activating GATA-3 transcription." (PMID 30100605, 2018). "We further interrogated Notch3 and GATA-3 mRNA in several breast cancer cell lines to validate results at the protein level." (PMID 30100605, 2018). "Other negatively correlated genes include well-established markers of luminal breast cancer: GATA3, FOXA1, and PGR." (PMID 29898756, 2018). "Using tumor xenograft models, we demonstrate herein that Notch3 restrains metastasis of breast cancer in vivo via regulation of GATA-3." (PMID 30100605, 2018). "The involvement of GATA3 in breast cancer, however, is complex as it was also shown to promote the growth of oestrogen-responsive tumours through direct binding to and activation of the oestrogen receptor α (ERα) gene." (PMID 30463912, 2018). "To date, there have been few investigations into the specific connection between Notch3 and GATA-3 in breast cancer cells." (PMID 30100605, 2018). "Solid evidence exists showing that, in breast cancer, the expression of GATA-3 is highly correlated to that of ERα, and the results were consistent with our previous findings." (PMID 30100605, 2018). "FOXA1 and GATA3 are involved in tumorigenesis and malignant progression in breast cancer cells in close correlation with the hormonal status." (PMID 30647855, 2018). "We therefore immunohistochemically stained ERα, FOXA1, and GATA3 in metastatic breast cancer specimens from various sites." (PMID 29972720, 2018). "The aim of this study was to analyze the expression of female breast cancer established markers NY-BR-1, GATA-3, mammaglobin, and BRST-2 in a cohort of male breast cancer in primary and metastatic lesions." (PMID 29116378, 2018). "To establish the pathological relevance of the anti-correlation between MYC overexpression and ESR1/GATA3 downregulation, we assessed the expression level of these ML-specific TFs in large cohorts of breast cancer samples." (PMID 29523784, 2018).